PAH (phenylalanine hydroxylase)
Diseases named in the same sentence as PAH in open-access papers (continued):
Sharing a sentence is not in itself a finding about the gene and the disease.
phenylketonuria (continued). "For example, in phenylketonuria (PKU) patients, phenylalanine accumulates in the plasma, cerebrospinal fluid and brain tissue due to a mutation in the gene encoding for phenylalanine hydroxylase (PAH)." (PMID 29367352, 2018). "Phenylketonuria (PKU), one of the most common metabolism-related diseases in humans, is caused by a recessively inherited phenylalanine hydroxylase (Pah) deficiency and leads to profound cognitive disability owing to Phe accumulation." (PMID 30038322, 2018). "Phenylketonuria (PKU; OMIM 261600) is an inherent disorder of metabolism predominantly caused by mutations in the phenylalanine hydroxylase (PAH) gene, which results in the accumulation of phenylalanine (Phe)." (PMID 29596327, 2018). "Genetic analysis showed that six cases carried PAH mutants and one case carried PTS mutant in patients with phenylketonuria, suggesting that mutations in PAH gene are the predominant cause of phenylketonuria in Jining." (PMID 29731766, 2018). "Phenylketonuria (PKU) is an inborn error of amino acid metabolism with an autosomal recessive inheritance caused in most cases by mutations in the phenylalanine hydroxylase (PAH) gene." (PMID 28540274, 2017). "HGD mediated continuous expression of phenylalanine hydroxylase (PAH) in the mouse liver, played therapeutic roles in the mouse with human phenylketonuria characteristics, by adjusting the level of phenylalanine in blood." (PMID 28912718, 2017). "Phenylketonuria (PKU), which primarily results from a deficiency of phenylalanine hydroxylase (PAH), is one of the most common inherited inborn errors of metabolism that impairs postnatal cognitive development." (PMID 28982351, 2017). "Phenylketonuria (PKU) is a genetic disease characterized by the inability to convert dietary phenylalanine to tyrosine by phenylalanine hydroxylase." (PMID 28520731, 2017). "Phenylketonuria (PKU, MIM 261600) is an autosomal recessive disorder caused by a deficiency of the enzyme phenylalanine-4-hydroxylase (PAH, EC 1.14.16.1), which is mainly active in the liver." (PMID 26822130, 2016). "The phenylalanine hydroxylase ( PAH) gene (MIM:612349) is the well-known responsible gene for classic phenylketonuria (PKU)." (PMID 27540528, 2016). "The variable numbers of tandem-repeat (VNTR) alleles at the phenylalanine hydroxylase (PAH) gene have been used in carrier detection and prenatal diagnosis in phenylketonuria families." (PMID 26025954, 2015). "Phenylketonuria (PKU) is an inherited autosomal recessive disorder of phenylalanine metabolism, mainly caused by a deficiency of phenylalanine hydroxylase (PAH)." (PMID 26503515, 2015). "Phenylketonuria (PKU; McKusick 261600) is caused by deficiency of phenylalanine hydroxylase, resulting in excessively elevated blood phenylalanine concentrations and normal to slightly decreased blood tyrosine concentrations." (PMID 24422943, 2014). "In humans, mutations that inactivate the PAH gene are associated with a disease known as phenylketonuria (PKU), characterized by the accumulation of the toxic metabolites of phenylalanine, phenylpyruvate and phenyllactate, that are responsible for severe neurologic anomalies and premature death." (PMID 24409310, 2014). "Phenylketonuria (PKU; OMIM#261600) is an inherited metabolic cause of mental disability due to the defect of the phenylalanine hydroxylase (PAH) enzyme that converts phenylalanine (Phe) into tyrosine (Tyr)." (PMID 25003100, 2014). "Phenylketonuria (PKU), caused by a deficiency of phenylalanine hydroxylase, is the most common clinically encountered inborn error of amino acid metabolism." (PMID 25548658, 2014). "In phenylketonuria (PKU, OMIM 261600), deficiency of the enzyme phenylalanine hydroxylase (PAH) leads to increased phenylalanine (Phe) concentrations." (PMID 23842451, 2013).
phenylketonuria (continued). "Phenylketonuria (PKU), an autosomal recessive disorder of amino acid metabolism caused by mutations in the phenylalanine hydroxylase (PAH) gene, leads to childhood mental retardation by exposing neurons to cytotoxic levels of phenylalanine (Phe)." (PMID 23940767, 2013). "Pleiotropy in humans is ubiquitous; there are multiple examples in the literature, starting with a textbook example of phenylketonuria (PKU), caused by a deficiency of the enzyme phenylalanine hydroxylase, which is necessary to convert the essential amino acid phenylalanine to tyrosine." (PMID 22934054, 2012). "Phenylketonuria (PKU) is a metabolic disorder caused by impaired phenylalanine hydroxylase (PAH)." (PMID 19172175, 2009). "Phenylketonuria (PKU) is a rare inherited metabolic disorder resulting from pathogenic variants in the phenylalanine hydroxylase (PAH) gene, leading to markedly reduced or absent activity of the PAH enzyme." (PMID 41228482, 2025). "Phenylketonuria (PKU), an inherited metabolic disorder affecting approximately 1 in 10,000 to 1 in 15,000 individuals globally, is characterized by the deficiency in phenylalanine hydroxylase (PAH) enzyme, which is pivotal for the metabolism of amino acid phenylalanine." (PMID 40500796, 2025). "Extensive studies have examined the clinical manifestations, pathogenic mechanisms, and genetic variations of phenylketonuria (PKU) across different populations, resulting in a substantial collection of molecular genetic data on the phenylalanine hydroxylase (PAH) gene and its variants." (PMID 40730740, 2025). "Phenylketonuria (PKU) is an inherited disorder, a rare autosomal recessive inborn error of phenylalanine (Phe) metabolism caused by pathogenic variants in the gene encoding phenylalanine hydroxylase (PAH)." (PMID 38383420, 2024). "A classic example is phenylketonuria (PKU), in which mutations in the phenylalanine hydroxylase gene only cause neuronal injury in the presence of dietary phenylalanine in the environment—both genetic and environmental factors need to be present for the disorder to manifest." (PMID 36845417, 2023). "Phenylketonuria (PKU, OMIM:261600) is the most common congenital, autosomal recessive, metabolism disorder and is caused by homozygous or compound heterozygous mutations in the Phenylalanine hydroxylase (PAH) gene on chromosome 12q23." (PMID 37098607, 2023). "Phenylketonuria (PKU) is a rare inherited metabolic disorder characterized by the partial or total inability to convert the essential amino acid Phenylalanine (Phe) into Tyrosine (Tyr) due to biallelic pathogenetic mutations of the liver enzyme phenylalanine hydroxylase (PAH)." (PMID 38069347, 2023). "Phenylketonuria (PKU) results from a defective function of the enzyme phenylalanine hydroxylase." (PMID 38091797, 2023). "Phenylketonuria (PKU; OMIM 261600) is the most prevalent inborn error of the metabolism (IEM) caused by mutations in the phenylalanine hydroxylase (PAH, OMIM * 612349) gene which catalyzes the hydroxylation of phenylalanine (Phe) to tyrosine (Tyr) using tetrahydrobiopterin (BH4) as a cofactor." (PMID 35328070, 2022). "Phenylketonuria (PKU, OMIM # 261600) stems from the body’s inability to metabolize the essential amino acid phenylalanine (Phe) to tyrosine (Tyr) due to deficient activity of phenylalanine hydroxylase (PAH) with resultant cognitive impairment." (PMID 34575895, 2021). "Phenylketonuria and hyperphenylalaninemia (PKU and HPA; OMIM 261600) are inborn errors of metabolism (IEMs) due to mutations in the PAH gene, normally coding for the liver enzyme phenylalanine hydroxylase (PAH, EC 1.14.16.1), which converts the aminoacid phenylalanine (Phe) into tyrosine (Tyr)." (PMID 34828453, 2021). "Phenylketonuria (PKU, OMIM 261600) is an inborn error of phenylalanine (Phe) metabolism caused in most cases (98%) by an inherited deficiency in l-phenylalanine-4-hydroxylase (PAH; EC 1.14.16.1) activity, leading to elevated levels of Phe in body fluids." (PMID 32698408, 2020).
phenylketonuria (continued). "Phenylketonuria (PKU, OMIM 261600) is an autosomal recessive metabolic disease caused by mutations of the phenylalanine hydroxylase (PAH) gene (*612349), which leads to the incomplete hepatic conversion of the essential amino acid phenylalanine (Phe) to tyrosine (Tyr)." (PMID 31993977, 2020). "Beyond sapropterin, a phenylalanine hydroxylase endogenous ligand used since 2007 in the treatment of phenylketonuria (see Section 3.1), the anti-aggregative protein binder tafamadis was approved in 2012 against the neurodegenerative disease transthyretin-related hereditary amyloidosis." (PMID 32660097, 2020). "Phenylketonuria (OMIM # 261600) is an autosomal recessive disorder caused by mutations in the PAH gene, leading to a deficiency in the enzyme responsible for the hydroxylation of phenylalanine to tyrosine, phenylalanine hydroxylase (EC 1.14.16.1)." (PMID 32397259, 2020). "Phenylketonuria (PKU) is an autosomal recessive genetic disease, caused by the phenylalanine hydroxylase (PAH) deficiency in the metabolic pathway, which prevents phenylalanine from being converted into tyrosine, leading to a large amount of phenylalanine discharged from the urine." (PMID 31382905, 2019). "Phenylketonuria is an autosomal recessive metabolic liver disease in which the impaired activity of the enzyme phenylalanine hydroxylase (PAH) leads to a decreased metabolism of phenylalanine (L-Phe) and its accumulation in blood, resulting in systemic hyperphenylalaninaemia." (PMID 31117296, 2019). "Phenylketonuria (PKU), one of the most prevalent inborn errors of metabolism, is caused by the inability to adequately degrade the amino acid phenylalanine, due to a deficiency of the enzyme phenylalanine hydroxylase." (PMID 30209646, 2018). "Phenylketonuria (PKU), or phenylalanine hydroxylase deficiency (PAHD), is a rare autosomal recessive disease, induced by the deficiency of the hepatic enzyme, phenylalanine hydroxylase (PAH) that converts the essential amino acid phenylalanine (PHE) into tyrosine (TYR)." (PMID 28274259, 2017). "Phenylketonuria (PKU; McKusick #261600) is a rare autosomal recessive inborn error of phenylalanine (Phe) metabolism caused by variants in the gene encoding phenylalanine hydroxylase (PAH)." (PMID 29025426, 2017). "Phenylketonuria (PKU, OMIM 261600) is an autosomal recessive disorder characterized by high plasma levels of phenylalanine (Phe) due to pathogenic variations in the PAH gene, which encodes phenylalanine hydroxylase (PAH, EC 1.14.16.1)." (PMID 27336782, 2016). "Phenylketonuria (PKU; OMIM 261600) is an inborn error of metabolism characterized by the inability to convert phenylalanine (Phe) to tyrosine (Tyr), caused by the deficiency of hepatic phenylalanine hydroxylase (EC 1.14.16.1)." (PMID 24007597, 2013). "Pathological activation of α-Klotho may be implicated in phenylketonuria (PKU), an autosomal recessive disorder caused by a deficiency of phenylalanine hydroxylase, an enzyme that catalyzes the conversion of phenylalanine to tyrosine." (PMID 24062643, 2013). "Studies on preclinical models of phenylketonuria (PKU), an inherited metabolic disorder, have used two strains, BTBR and C57Bl/6, created via a chemically induced point mutation in the gene encoding the enzyme phenylalanine hydroxylase (BTBRenu2 and C57enu2, respectively)." (PMID 41677594, 2026). "Phenylketonuria (PKU), one of the most common genetic metabolic disorders, is due to defective activity of phenylalanine hydroxylase (PAH), a member of the aromatic amino acid hydroxylases." (PMID 41322342, 2026). "Phenylketonuria (PKU; MIM:261600) is primarily caused by missense mutations in the gene encoding phenylalanine hydroxylase (PAH), the enzyme responsible for the hydroxylation of phenylalanine to produce tyrosine." (PMID 41462762, 2025). "Phenylketonuria (PKU, MIM 261600) results from a deficiency in the hepatic enzyme phenylalanine hydroxylase (PAH; EC 1.14.16.1; OMIM 612349)." (PMID 39064614, 2024).
phenylketonuria (continued). "Phenylketonuria (PKU, OMIM 261600), an inborn error of metabolism, is defined by the dysfunction of phenylalanine hydroxylase (PAH) caused by a defect in the PAH gene." (PMID 38999811, 2024). "Phenylketonuria (PKU, OMIM #261600) is an autosomal recessive amino acid metabolism disorder caused by compound heterozygous mutations of the phenylalanine hydroxylase (PAH) gene on chromosome 12." (PMID 39093767, 2024). "Phenylketonuria (PKU, OMIM 261600) is an autosomal recessive inherited disease characterised by elevated plasma phenylalanine (Phe) levels due to mutations in the phenylalanine hydroxylase (PAH)." (PMID 39599702, 2024). "Phenylketonuria (PKU) is an inherited metabolic disease where a defect in coding for the enzyme, phenylalanine hydroxylase (PAH) results in an inability, or severely reduced ability, to metabolize the amino acid phenylalanine (Phe) into tyrosine." (PMID 39639994, 2024). "Phenylketonuria (PKU; OMIM 261600) is a hereditary metabolic disorder characterized by a deficiency of the enzyme phenylalanine hydroxylase, which converts the amino acid phenylalanine to tyrosine." (PMID 39408322, 2024). "Phenylketonuria (PKU, OMIM 261600) is an inherited autosomal recessive disorder of amino acid metabolism caused by a deficiency of phenylalanine hydroxylase (PAH)." (PMID 39064647, 2024). "Phenylketonuria (PKU) (OMIM # 261,600) is an inherited metabolic disorder (IMD) resulting from gene mutations that impair the function of the enzyme phenylalanine hydroxylase (PAH)." (PMID 37349772, 2023). "Phenylketonuria (PKU; OMIM#261600) is a genetic metabolic disease caused by the deficiency of phenylalanine hydroxylase, a liver enzyme responsible for the conversion of phenylalanine to tyrosine." (PMID 36814307, 2023). "Phenylketonuria (PKU, MIM#261,600, ORPHAcode 716) is a rare genetic metabolic disease caused by the deficiency of the enzyme phenylalanine hydroxylase (EC 1.14.16.1) that converts phenylalanine (Phe) to tyrosine." (PMID 37291632, 2023). "Phenylketonuria (PKU) is a rare autosomal recessive inborn error of the metabolism, in which the impaired activity of phenylalanine hydroxylase leads to the accumulation of phenylalanine (Phe) in the blood, which becomes toxic in the brain." (PMID 38140353, 2023). "Phenylketonuria (PKU) (PKU, OMIM # 261,600) is an inherited disorder of amino acid metabolism caused by pathogenic variations in the phenylalanine hydroxylase (PAH) gene, which encodes the PAH enzyme." (PMID 37447372, 2023). "A recent study showed that the mouse lncRNAPair and humanHULC, which are associated with phenylalanine hydroxylase (PAH), are involved in the development of the inherited metabolic disorder phenylketonuria (PKU)." (PMID 36604148, 2022). "Phenylketonuria (PKU; OMIM 261600) is an inborn error of phenylalanine (Phe) metabolism, caused by a deficiency of the Phe hydroxylase (PAH; EC 1.14.16.1) enzyme." (PMID 36145250, 2022). "Phenylketonuria (PKU; OMIM #261600) is autosomal recessive disorder characterized by a deficiency of the phenylalanine hydroxylase (PAH; EC 1.14.16.1), an enzyme required to metabolize the amino acid phenylalanine (Phe)." (PMID 36235708, 2022). "Phenylketonuria (PKU, MIM 261,600) is a deficiency in the hepatic enzyme phenylalanine hydroxylase (PAH; EC 1.14.16.1; OMIM 612,349) that occurs in approximately 1 in 24,000 people, with an estimated 450,000 individuals affected worldwide." (PMID 35854334, 2022). "Phenylketonuria (PKU) is an autosomal recessive phenylalanine metabolism mistake due to defects in the enzyme phenylalanine hydroxylase, which converts phenylalanine to tyrosine." (PMID 36138787, 2022). "Phenylketonuria (PKU, OMIM # 261,600) is an inborn error of phenylalanine (Phe) metabolism caused by deficiency of phenylalanine hydroxylase." (PMID 33581730, 2021).
phenylketonuria (continued). "Phenylketonuria (PKU, OMIM 261600) is an autosomal recessive disorder of phenylalanine (Phe) metabolism caused by deficiency of phenylalanine hydroxylase (PAH), encoded by the PAH gene." (PMID 33728249, 2021). "Thirteen exons of the PAH gene were sequenced in 84 cases with phenylketonuria (PKU) diagnosed during neonatal genetic and metabolic disease screening in Shaanxi province, and their mutations were analyzed." (PMID 33564846, 2021). "Phenylketonuria (PKU; MIM #261600) is an autosomal recessive disorder caused by the deficiency of the enzyme phenylalanine hydroxylase (PAH; E.C.1.14.16.1), which is encoded by the phenylalanine hydroxylase gene (PAH, MIM * 612349; 12q23.2)." (PMID 34828281, 2021). "The metabolic disease phenylketonuria (PKU) is characterized by the absence or disrupted function of the phenylalanine hydroxylase (PAH) enzyme." (PMID 34711827, 2021). "Phenylketonuria (PKU) is a rare genetic disease that results in reduced activity of the enzyme, phenylalanine hydroxylase, which converts the essential amino acid, phenylalanine (Phe) to tyrosine." (PMID 33990606, 2021). "Phenylketonuria (PKU) is an inborn error of phenylalanine (Phe) metabolism in which the enzyme phenylalanine hydroxylase that metabolises Phe to tyrosine is functionally impaired due to variants in the PAH gene." (PMID 34412683, 2021). "Phenylketonuria (PKU), triggered by recessively inherited phenylalanine hydroxylase (PAH) defect, represents one of the widely popular neonatal faults of metabolism (IEMs)." (PMID 34977000, 2021). "Phenylketonuria (PKU, OMIM 261600) is an autosomal recessive disorder of phenylalanine metabolism characterized by deficient phenylalanine hydroxylase (PAH, EC 1.14.16.1)." (PMID 34677395, 2021). "Phenylalanine hydroxylase (PAH) deficiency leads to phenylalanine accumulation and results in phenylketonuria (PKU)." (PMID 32883979, 2020). "Phenylketonuria (PKU; OMIM 261600) is an inherited, autosomal recessive disorder caused by a deficiency in the enzyme phenylalanine hydroxylase (PAH)." (PMID 32358708, 2020). "Phenylketonuria (PKU; OMIM#261600) is a rare metabolic disorder caused by mutations in the phenylalanine hydroxylase (PAH) gene resulting in high phenylalanine (Phe) in blood and brain." (PMID 32106880, 2020). "Phenylketonuria (PKU) is a common inborn error of amino acid metabolism in which the enzyme phenylalanine hydroxylase, which converts phenylalanine to tyrosine, is functionally impaired due to pathogenic variants in the PAH gene." (PMID 33375644, 2020). "Phenylketonuria (PKU) is a rare, inherited metabolic disorder (IMD) caused by phenylalanine hydroxylase deficiency, leading to an abnormal accumulation of blood phenylalanine." (PMID 32722073, 2020). "Defective function of phenylalanine hydroxylase in phenylketonuria (PKU) results in the accumulation of phenylalanine (Phe) and the reduction of tyrosine (Tyr) in the blood, interfering in the normal development and function of organs and tissues in the body." (PMID 31993977, 2020). "Phenylketonuria (PKU, OMIM 261600) is an autosomal recessive genetic disorder caused by mutations of the gene encoding the phenylalanine hydroxylase (PAH, EC1.14.16.1) enzyme." (PMID 31640267, 2019). "One example of a known IEM associated with ASD is phenylketonuria (PKU; OMIM 261600), a disorder due to defects in the phenylalanine hydroxylase enzyme system." (PMID 31551836, 2019). "Phenylketonuria is an inherited disorder resulting in decreased metabolism of the amino acid phenylalanine as a result of a mutation in the gene for the hepatic enzyme phenylalanine hydroxylase (PAH), rendering it non-functional." (PMID 31619961, 2019). "Phenylketonuria (PKU; OMIM 262600) is an autosomal recessive inborn error of phenylalanine metabolism caused by a deficiency of the phenylalanine hydroxylase (PAH) enzyme." (PMID 30621767, 2019).